RBM8A (RNA binding motif protein 8A)
Description:
Required for pre-mRNA splicing as component of the spliceosome. Core component of the splicing-dependent multiprotein exon junction complex (EJC) deposited at splice junctions on mRNAs. The EJC is a dynamic structure consisting of core proteins and several peripheral nuclear and cytoplasmic associated factors that join the complex only transiently either during EJC assembly or during subsequent mRNA metabolism. The EJC marks the position of the exon-exon junction in the mature mRNA for the gene expression machinery and the core components remain bound to spliced mRNAs throughout all stages of mRNA metabolism thereby influencing downstream processes including nuclear mRNA export, subcellular mRNA localization, translation efficiency and nonsense-mediated mRNA decay (NMD). The MAGOH-RBM8A heterodimer inhibits the ATPase activity of EIF4A3, thereby trapping the ATP-bound EJC core onto spliced mRNA in a stable conformation. The MAGOH-RBM8A heterodimer interacts with the EJC key regulator PYM1 leading to EJC disassembly in the cytoplasm and translation enhancement of EJC-bearing spliced mRNAs by recruiting them to the ribosomal 48S preinitiation complex. Its removal from cytoplasmic mRNAs requires translation initiation from EJC-bearing spliced mRNAs. Associates preferentially with mRNAs produced by splicing. Does not interact with pre-mRNAs, introns, or mRNAs produced from intronless cDNAs. Associates with both nuclear mRNAs and newly exported cytoplasmic mRNAs. The MAGOH-RBM8A heterodimer is a component of the nonsense mediated decay (NMD) pathway. Involved in the splicing modulation of BCL2L1/Bcl-X (and probably other apoptotic genes); specifically inhibits formation of proapoptotic isoforms such as Bcl-X(S); the function is different from the established EJC assembly.
Synonyms: RBM8; MDS014; ZNRP; BOV-1A; BOV-1B; BOV-1C; Y14; C1DELq21.1; DEL1q21.1; TAR; ZRNP1
Tractability: Small molecule: a structure with a bound ligand is known. PROTAC: UniProt records ubiquitination sites on it; ubiquitination databases record sites on it; its protein half-life has been measured.
Gene: Protein-coding gene on chromosome 1 (145,921,065 to 145,928,067, reverse strand). Ensembl gene ENSG00000265241.
Subcellular location: Nucleus; Nucleus speckle; Cytoplasm
Subcellular location (Human Protein Atlas): Nuclear speckles
Pathways (Reactome):
Metabolism of RNA: Nonsense Mediated Decay (NMD) enhanced by the Exon Junction Complex (EJC); Transport of Mature mRNA derived from an Intron-Containing Transcript; mRNA 3'-end processing; mRNA Splicing - Major Pathway
Developmental Biology: Regulation of expression of SLITs and ROBOs
Gene Ontology:
Molecular function: protein binding; RNA binding; mRNA binding; nucleic acid binding
Biological process: mRNA export from nucleus; mRNA metabolic process; mRNA splicing, via spliceosome; nuclear-transcribed mRNA catabolic process, nonsense-mediated decay; regulation of alternative mRNA splicing, via spliceosome; regulation of mRNA processing; regulation of nuclear-transcribed mRNA catabolic process, nonsense-mediated decay; RNA splicing; RNA processing
Cellular component: catalytic step 2 spliceosome; cytoplasm; exon-exon junction complex; exon-exon junction subcomplex mago-y14; nuclear speck; nucleus; post-spliceosomal complex; spliceosomal complex; U2-type catalytic step 1 spliceosome; U2-type catalytic step 2 spliceosome; cytosol; nucleoplasm; dendrite; neuronal cell body
Genetic constraint (gnomAD): Loss-of-function variants: 8 observed, 26.45 expected, observed/expected ratio (o/e) 0.3, 90% interval 0.18 to 0.55. The upper end of that interval is the gene's LOEUF score, 0.55, which puts it in group 2 of 6, group 1 being the genes least tolerant of losing a copy. Missense variants: 114 observed, 244.02 expected, observed/expected ratio (o/e) 0.47, 90% interval 0.4 to 0.55. Synonymous variants: 66 observed, 83.03 expected, observed/expected ratio (o/e) 0.79, 90% interval 0.65 to 0.98.
Gene-disease validity (ClinGen):
ClinGen rates the evidence that RBM8A causes each of these diseases.
thrombocytopenia-absent radius syndrome (autosomal recessive): Definitive.
Homologues: Orthologues: chimpanzee RBM8A (100% identical), macaque RBM8A (100% identical), mouse Rbm8a (100% identical), pig RBM8A (100% identical), rabbit RBM8A (100% identical), rat Rbm8a (100% identical), dog RBM8A (99% identical), mouse Rbm8a2 (98% identical), zebrafish rbm8a (94% identical), tropical clawed frog rbm8a (93% identical), guinea pig RBM8A (91% identical), Drosophila melanogaster tsu (61% identical), and 1 more.
Diseases named in the same sentence as RBM8A in open-access papers:
RBM8A is named in the same sentence as 92 diseases in open-access papers, as found by Europe PMC text mining. Sharing a sentence is not in itself a finding about the gene and the disease. The quoted sentences say what the papers report.
Thrombocytopenia (15 papers, 2013 to 2025). A reduction in the number of circulating thrombocytes. "TAR syndrome is characterized by a variable degree of radial defects and neonatal thrombocytopenia, resulting from a heterozygous deletion of one allele on chromosome 1 and another mutation in the RBM8A gene." (PMID 38541032, 2024). "A second instance is that of a heterozygous 200 kb deletion in RBM8A causing thrombocytopenia-absent radius-TAR syndrome (OMIM#274000) only when inherited in trans with a heterozygous c.-21G>A common polymorphism." (PMID 40430072, 2025). "Thrombocytopenia with absent radius (TAR) syndrome is often caused by a 1q21.1 deletion together with a sequence variant within an RBM8A regulatory element, highlighting the importance of displaying all variant types within a single interface." (PMID 37285546, 2023). "Third, the genetic basis of most cases of TAR (thrombocytopenia with absent radii) syndrome is a null allele of RBM8A coupled with a rare polymorphism that creates an EVI1 binding site at the RBM8A promoter, resulting in greatly reduced levels of RMB8A expression." (PMID 25849990, 2015). "Thus, a submicroscopic deletion of 1q21.1 (encompassing the RBM8A gene) has been reported to interact with a low-frequency functional SNP in the regulatory region of the wild-type RBM8A allele to cause thrombocytopaenia with absent radii." (PMID 23820649, 2013). "Besides, mutations in Rbm8a lead to thrombocytopenia-absent radius syndrome." (PMID 34249098, 2021). "Among these cases we encountered two fetuses with thrombocytopenia-absent radius syndrome - TAR (OMIM#274000) and in both cases we confirmed compound heterozygosity for typical 1q21.1 deletion and the hypomorphic nucleotide change in the RBM8A gene on the other allele." (PMID 27846804, 2016). "Recently, platelet RNA-seq successfully revealed abnormal splicing events in 1) NBEAL2, thus identifying the gene responsible for the Gray Platelet Syndrome, and, 2) the RNA-binding protein RBM8A, thus uncovering the gene responsible for the TAR (=thrombocytopenia and absent radii) syndrome." (PMID 23323973, 2013).
microcephaly (13 papers, 2016 to 2023). A congenital or acquired developmental disorder in which the circumference of the head is smaller than normal for the person's age and sex. "In mice, it has been demonstrated that haploinsufficiency in Magoh, Rbm8a, or Eif4a3 is sufficient to cause microcephaly in mice, indicating that these components are necessary in neurogenesis." (PMID 35406756, 2022). "Microdeletions of 1q21.1 chromosome, which include Rbm8a gene, were associated with abnormal brain developments such as microcephaly or macrocephaly as well as moderate mental retardation." (PMID 35509884, 2022). "Haploinsufficiency of Rbm8a has been found to cause apoptosis and the manifestation of microcephaly in mice." (PMID 35406756, 2022). "These defects lead to impaired cortical development and microcephaly, a phenotype also associated with RBM8A and EIF4A3 mutations in humans." (PMID 32502192, 2020). "In mice, loss of a single copy of Rbm8a or other EJC genes (Magoh or Eif4e) causes microcephaly and severe neural defects." (PMID 32773035, 2020). "Our mouse phenotype is consistent with genetic studies on humans, which have associated RBM8A with neurodevelopmental disorders, such as microcephaly." (PMID 33154347, 2020). "The neural cell death phenotype is similar to that seen in mouse heterozygous EJC mutant embryos, and is consistent with the microcephaly phenotype in human patients heterozygous for hypomorphic RBM8A and EIF4A3 mutations." (PMID 32502192, 2020). "Microdeletions and duplications of a 15-gene locus containing RBM8A are associated with microcephaly, macrocephaly, autism, and epilepsy." (PMID 27618312, 2016). "Amongst the 3 core EJC components, reduced RBM8A levels are the most strongly associated with human microcephaly." (PMID 27618312, 2016). "Both Eif4a3 and Rbm8a haploinsufficiency caused severe microcephaly, with an average 70% reduction in cortical area of whole mount brains." (PMID 27618312, 2016). "We previously showed that NSC-specific haploinsufficiency for either Magoh or Rbm8a causes microcephaly in mice." (PMID 27618312, 2016). "The RBM8A gene, also known as Y14, is another essential neurogenesis regulator, is located on 1q21.1 and microdeletions within this region are associated to a wide range of human diseases, including microcephaly." (PMID 37881689, 2023). "Thus, our results demonstrate that Rbm8a is essential for the neurodevelopment, and loss of even one copy of this gene can lead to the severe phenotypes, including microcephaly, a disruption in the excitatory/inhibitory (E/I) balance in the brain and early postnatal lethality." (PMID 33154347, 2020). "The resulting Rbm8a haploinsufficient mice were significantly smaller compared to littermate controls and had microcephaly, which is a greater than 50% reduction in brain size at P17." (PMID 36902031, 2023). "The microcephaly phenotypes are significantly more severe in Rbm8a and Eif4a3 mutant mice, with an average reduction of 70%, compared to Magoh in postnatal brains." (PMID 36142288, 2022).
microcephaly (continued). "Rbm8a cKO in neural stem cells results in early postnatal lethality, microcephaly, and leads to decreased number of PV+ and NPY+ cortical interneurons, abnormal distribution of PV+, SST+, and NPY+ interneurons in the cortex, and aberrant GABA transmission." (PMID 33154347, 2020). "When Rbm8a is selectively knocked out in neural stem cells, the resulting mice exhibit microcephaly, early postnatal lethality, and altered distribution of excitatory neurons in the neocortex." (PMID 33154347, 2020). "While knockout of Upf1 and other NMD factors is embryonic lethal in mice, mice haploinsufficient for the EJC components Magoh, Rbm8a, and Eif4a3 exhibit aberrant neurogenesis and microcephaly (20, –, 22)." (PMID 30401782, 2018). "Using a new conditional allele, we first show that Eif4a3 haploinsufficiency phenocopies aberrant neurogenesis and microcephaly of Magoh and Rbm8a mutant mice." (PMID 27618312, 2016). "Further, mice heterozygous for either Magoh or Rbm8a exhibit aberrant neurogenesis and microcephaly." (PMID 27618312, 2016). "First, we generated a NSC-specific conditional Eif4a3 mouse model to demonstrate that Eif4a3 haploinsufficiency phenocopies the aberrant neurogenesis and microcephaly seen in Rbm8a and Magoh mutants." (PMID 27618312, 2016). "The microcephaly phenotype of Rbm8a and Eif4a3 mutant mice was significantly worse than Magoh haploinsufficient mice, which exhibited a 40% reduction." (PMID 27618312, 2016). "Conclusive evidence directly linking the EJC to early development came when MAGOH and RBM8A haploinsufficiency was shown to result in mouse microcephaly with follow up studies indicating high EJC enrichment in neural progenitors and the EJC being critical for cortical development." (PMID 35406756, 2022). "Interestingly, Magoh cKO leads to similar phenotypes as Rbm8a, namely microcephaly, abnormal asymmetric division and interneuron differentiation." (PMID 33154347, 2020). "However, mice haploinsufficient for NMD factors upstream of UPF1, including Magoh, Rbm8a, and Eif4a3, develop microcephaly (20, –, 22)." (PMID 30401782, 2018). "While these studies show Magoh and Rbm8a are essential for corticogenesis, it remains unknown if impairment of the third major EJC constituent, Eif4a3, causes microcephaly." (PMID 27618312, 2016). "Consistent with human patient studies, knockdown and knockout of Rbm8a in a mouse model revealed the critical role of RBM8A in neural progenitor cell (NPC) proliferation, neuronal migration and interneuron development, and loss of function in RBM8A in NPCs causes microcephaly." (PMID 34071723, 2021). "Moreover, haploinsufficiency of Rbm8a or Magoh in mice results in microcephaly." (PMID 30388411, 2018).
hepatocellular carcinoma (8 papers, 2019 to 2022). A malignant tumor that arises from hepatocytes. "In addition, for individuals with hepatocellular carcinoma, elevated RBM8A expression was associated with poor prognosis and progression-free survival." (PMID 33692831, 2021). "RBM8A is abnormally expressed in several types of tumors, including cervical cancer, non-small-cell lung carcinoma, myeloma, and hepatocellular carcinoma." (PMID 34804926, 2021). "Abnormal expression of RBM8A has been observed in many types of cancer, including cervical cancer, non-small-cell lung carcinoma, myeloma, gastric cancer, and hepatocellular carcinomas." (PMID 34804926, 2021). "RNA-binding motif protein 8A (RBM8A) is abnormally overexpressed in hepatocellular carcinoma (HCC) and involved in the epithelial-mesenchymal transition (EMT)." (PMID 33552961, 2020). "RBM8A was reported to predict poor prognosis and promote tumor progression in hepatocellular carcinoma, but its function in breast cancer remains unknown." (PMID 35568705, 2022). "In hepatocellular carcinoma, the expression level of RBM8A is significantly increased." (PMID 32294703, 2020). "Aberrant expression of RBM8A has been detected in various malignancies, including hepatocellular carcinoma (HCC) and glioblastoma (GBM)." (PMID 36105365, 2022). "We used sequencing data from the Cancer Genome Atlas database and Gene Expression Omnibus, analyzed RBM8A expression and gene regulation networks in hepatocellular carcinoma (HCC)." (PMID 30670676, 2019).
breast carcinoma (5 papers, 2017 to 2022). "The TCGA database contained a high level of RBM8A mutation in the following types of cancer: bladder cancer, liver cancer, lung cancer, breast cancer, uterine cancer, pancreas, melanoma, head neck, stomach, colorectal cancer, ccRCC, and pRCC." (PMID 34326876, 2021). "Using MCF-7 breast cancer cells as a model, we showed that the down-regulation of the EJC core factor, RBM8A, is one of the causes of mRNA re-splicing." (PMID 34204574, 2021). "Furthermore, RBM8A silencing decreased the DDP resistance in breast cancer cells by inhibiting the AKT/mTOR pathway." (PMID 36105365, 2022). "Taken together, these findings strongly suggested that HSPD1/RBM8A/G3BP1 could promote breast cancer progression and were correlated with poor prognosis." (PMID 35568705, 2022). "We further examined the correlation between circEIF3H and HSPD1/RBM8A/G3BP1 by qRT-PCT in 49 human breast cancer tissues and confirmed the positive correlation between circEIF3H and HSPD1/RBM8A/G3BP1 respectively." (PMID 35568705, 2022). "Furthermore, Kaplan–Meier survival analysis showed that breast cancer patients with high HSPD1, RBM8A, or G3BP1 expression respectively had significantly worse distant metastasis-free survival (DMFS) in the TCGA Cohort." (PMID 35568705, 2022). "Accumulating evidence showed that HSPD1, RBM8A, and G3BP1 played a key role in tumor progression in several cancers; however, its effect on breast cancer proliferation and metastasis remains unclear." (PMID 35568705, 2022).
gastric cancer (5 papers, 2020 to 2022). A primary or metastatic malignant neoplasm involving the stomach. "This study was designed to investigate the expression of RBM8A protein in patients with gastric cancer (GC) and to explore its correlation with clinical pathological features as well as prognosis." (PMID 32294703, 2020). "The results from real-time PCR demonstrated that 12 paired gastric cancer samples had significantly increased RBM8A expression levels compared to the paired adjacent tissues at mRNA levels, with an average upregulation fold of 6.89 (P<0.001)." (PMID 32294703, 2020). "We also detected the mRNA expression level of RBM8A in 16 pairs of gastric carcinoma tissues and adjacent tissues." (PMID 32294703, 2020). "The expression level of RBM8A was significantly higher in gastric carcinoma tissues compared to the adjacent tissues." (PMID 32294703, 2020). "In the present study, we sought to detect the vital expression of RBM8A protein in gastric carcinoma tissues and adjacent specimens, and further analyze its expression level with the clinicopathological features and prognosis." (PMID 32294703, 2020). "In present study, we found that the RBM8A mRNA and protein expression was increased in gastric carcinoma tissues compared with normal gastric tissues on the basis of immunohistochemistry and real time-PCR analysis." (PMID 32294703, 2020). "In this study, after analyzing 171 normal gastric tissues and 179 gastric carcinoma tissues based on TCGA database, a higher level of TPM of RBM8A in GC group was observed (P<0.05), indicating that RBM8A possessed more transcripts in gastric carcinoma tissues." (PMID 32294703, 2020). "We detected RBM8A mRNA levels in 16 paired adjacent tissues and gastric carcinoma tissues." (PMID 32294703, 2020). "In addition, gastric cancer patients with increased RBM8A expression have lower overall survival." (PMID 36105365, 2022).
glioblastoma (5 papers, 2021 to 2022). The most malignant astrocytic tumor (WHO grade IV). "Our previous study confirmed that RBM8A overexpression promoted glioblastoma growth and invasion through the Notch/STAT3 pathway." (PMID 35573726, 2022). "RBM8A increases cell proliferation and migration in glioblastoma tissues through the Notch/STAT3 pathway." (PMID 36142288, 2022). "A recent study on the effect of RBM8A knockdown in glioblastoma cells shows that it inhibits glioblastoma cell proliferation and invasion." (PMID 36142288, 2022). "The opposite effects have been detected in RBM8A overexpression that transwell analysis confirms an increase in cell migration and invasion of glioblastoma cells when RBM8A is overexpressed but a dramatic decrease when RBM8A is knocked down." (PMID 36142288, 2022).